PDE4DIP (phosphodiesterase 4D interacting protein)
Diseases named in the same sentence as PDE4DIP in open-access papers (continued):
Sharing a sentence is not in itself a finding about the gene and the disease.
cancer (19 papers, 2009 to 2024). A tumor composed of atypical neoplastic, often pleomorphic cells that invade other tissues. "Mutations in the PDE4DIP gene are common in cancers and are thought to be associated with cancer risk." (PMID 37355626, 2023). "Recently, accumulating evidence has implied that the PDE4DIP gene is associated with cancer risk." (PMID 37355626, 2023). "However, there is currently no systematic pan-cancer analysis of the association between PDE4DIP and various cancers." (PMID 37663233, 2023). "All in all, given the high mutation frequency of PDE4DIP in various cancers, we speculated that PDE4DIP mutations might be closely related to the development of cancers, which needs to be verified through subsequent experiments in different cancers." (PMID 37663233, 2023). "Furthermore, BC18 and descendant cells had mutations in the cancer-related genes (in PDE4DIP, as well as a back mutation in MTOR, and USP6) in comparison to normal cells, which may have contributed to turning this lineage into an active cancer line." (PMID 35951662, 2022). "In this study, we found that PDE4DIP had potential prognostic value in pan-cancer, including LAML and UVM, giving a new guidance for the diagnosis and treatment of cancers in the future." (PMID 37663233, 2023). "Consistent with previous reports, our study found that PDE4DIP expression was heterogeneous in different cancers, where it was up-regulated in some cancer types and down-regulated in others." (PMID 37663233, 2023). "PDE4DIP expression was also correlated with genetic variation, DNA methylation, immune cell infiltration, and immune-related genes in cancers." (PMID 37663233, 2023). "Through Cox regression analysis, we studied the relevance between PDE4DIP expression and four survival data of cancer patients, including OS, DSS, DFI, and PFI, to further reveal the potential prognostic value of PDE4DIP in different cancers." (PMID 37663233, 2023). "Functional enrichment analysis showed that PDE4DIP was mainly related to immune-related pathways in cancers, and in LAML, PDE4DIP was mainly related to immunoglobulin complexes, T-cell receptor complexes, and immune response regulatory signaling pathways." (PMID 37663233, 2023). "Our findings further provide more theoretical basis for using PDE4DIP as a biomarker for future immunotherapy of various cancers." (PMID 37663233, 2023). "In future research, we will collect more clinical data or design relevant experiments to further clarify the expression pattern of PDE4DIP in different cancers." (PMID 37663233, 2023). "Our study systematically revealed for the first time the potential prognostic and immunotherapeutic value of PDE4DIP in various cancers, including LAML." (PMID 37663233, 2023). "At the same time, the specific role of PDE4DIP in cancers, especially in LAML, still needs to be further clarified through molecular experiments." (PMID 37663233, 2023). "Based on the multiple public databases and online websites, we conducted comprehensive analyses for PDE4DIP in various cancers, including differential expression, prognosis, genetic variation, DNA methylation, and immunity." (PMID 37663233, 2023). "Prognostic analysis based on OS, DSS, DFI, and PFI indicated that high expression of PDE4DIP had a potential prognostic effect on some cancers, with a poor prognosis in LAML, PCPG, THYM, UVM, and HNSC patients, and a good prognosis in PAAD and PCPG patients." (PMID 37663233, 2023). "Our study revealed that PDE4DIP expression was markedly correlated with immune cell infiltration and the expression of immune-related genes in various cancers." (PMID 37663233, 2023). "Previous studies have found that PDE4DIP exhibits abnormal expression in various diseases, including malignant tumors, but its effect on the diagnosis, prognosis, and TME of tumors remains to be further explored." (PMID 37663233, 2023).
cancer (continued). "The results showed that there was a significant positive correlation between TAM infiltration levels and PDE4DIP expression in most cancers, mainly including M2-like TAMs." (PMID 37663233, 2023). "The somatic mutations of the organoids were identified and cancer genes in the most relevant BC genes were also found, including ERBB4, HLA-DRB1, PDE4DIP, PTPN22." (PMID 32774159, 2020). "GSEA of single gene determined the pathways affected by PDE4DIP expression in pan-cancer." (PMID 37663233, 2023). "Our research mainly studied the potential role of PDE4DIP expression in multiple cancer types based on online public databases, which may have systematic errors and lack of large-scale clinical cohort data for further analysis and verification." (PMID 37663233, 2023). "However, the specific regulatory mechanism of PDE4DIP expression in different cancers needs further exploration in subsequent studies." (PMID 37663233, 2023). "Notably, gene co-expression analysis revealed that PDE4DIP expression was significantly positively related to the expression of most immunoinhibitors in cancers." (PMID 37663233, 2023). "In addition, we compared the expression patterns of PDE4DIP at the mRNA and protein levels, and the results showed that in some cancer types, the expression patterns of PDE4DIP at the mRNA and protein levels were inconsistent, such as in PAAD and LUAD." (PMID 37663233, 2023). "It is speculated that PDE4DIP may serve as an oncogene in these cancers, possibly promoting tumor development." (PMID 37663233, 2023). "In order to fully elucidate the important role of PDE4DIP in multiple cancer types, we conducted a systematic pan-cancer analysis of the PDE4DIP gene based on The Cancer Genome Atlas (TCGA) and the Genotype-Tissue Expression (GTEx) public databases in this study." (PMID 37663233, 2023). "Therefore, our study is the first to comprehensively and systematically analyze the expression, prognosis, genetic changes, DNA methylation, immune cell infiltration, immune-related genes, and biological functions of PDE4DIP in many cancers." (PMID 37663233, 2023). "Furthermore, we analyzed the expression of PDE4DIP at the protein level in different cancers based on the CPTAC data set." (PMID 37663233, 2023). "On the one hand, differences in gene expression regulatory networks between different cancer types might result in different regulatory mechanisms of PDE4DIP, leading to different expression patterns in cancers." (PMID 37663233, 2023). "In the second dataset, LUSC, PIK3CA (46.5%), EGFR (7%), PDE4DIP (6.6%), KRAS (4.4%), and RELN (4.4%) were labeled with copy number gain, while CDKN2A (27.9%), LRP1B (17.4%), PTEN (9.8%), and PTPRD (9%) appeared to be the cancer genes with copy number loss." (PMID 35330454, 2022). "In addition, we found in this list established cancer genes involved in other types of cancer, such as PDE4DIP, SF3B1, AHNAK, COPB2, CSDE1, KIF5B, NDUFA10, RSRC2." (PMID 31949199, 2020). "Using the CCLE mutation dataset containing 27/38 bortezomib-insensitive and 22/49 bortezomib-sensitive cancer cell lines, we were able to show consistently elevated mutation frequencies for 18/19 genes (not PDE4DIP) in bortezomib-insensitive cell lines compared to bortezomib-sensitive cell lines." (PMID 39127727, 2024). "Together, these findings suggest that PDE4DIP may play a critical role in cancer." (PMID 37355626, 2023). "Thus, this study aimed to elucidate the potential functions of PDE4DIP in various cancers." (PMID 37663233, 2023). "However, the biological function of PDE4DIP in human cancer remains obscure." (PMID 37355626, 2023).
cancer (continued). "However, the role of PDE4DIP in cancers is poorly understood." (PMID 34422903, 2021). "Genes LGALS8, PDE4DIP, RAD17, ELN, MUC4 and SEMA4D had a mid-range expression in both cancer types, while OPRM1 and ADRA1 were the least expressed, thereby corroborating the results from our box plot and survival analysis." (PMID 38544823, 2024). "Our study reveals a novel PDE4DIP-mediated PKCε/NF1/RAS signal transduction axis and highlights PDE4DIP as a promising therapeutic target for KRAS-mutant cancers." (PMID 37355626, 2023). "However, the functional roles of PDE4DIP in human cancer remain unknown." (PMID 37355626, 2023). "Four cancer‐driver genes NOTCH2, ASXL1, PDE4DIP, and MUC4 were found to be selectively amplified in both hESC‐RPE and HS980 (p38) samples." (PMID 32319201, 2020). "Our research revealed that the PDE4DIP gene had potential prognostic and immunotherapeutic values in various cancers, including LAML, providing a certain theoretical basis for using PDE4DIP as a biomarker in future cancer treatment." (PMID 37663233, 2023). "The following most altered cancer genes were LRP1B (26%), PIK3CA (24%), CDKN2A (24%), PTPRD (15%), RB1 (13%), PDE4DIP (13%), PCLO (11%), KRAS (11%), FAT1 (10%), and RELN (10%), and these results partially overlap with the most altered genes depicted in the experimental cohort." (PMID 35330454, 2022). "Besides, the somatic mutations of the organoids were identified and cancer mutant genes in the most relevant BC genes were also found, including ERBB4, HLA-DRB1, PDE4DIP, PTPN22." (PMID 32774159, 2020). "However, the full picture of PDE4DIP in pan-cancer has not been reported." (PMID 37663233, 2023). "In SCLC, it can be observed that cancer gene alterations appear to be more frequent in women, the most consistent differences being observed in PTRD, CREBBP, GRM3, ATRX, NOTCH3, and PDE4DIP, while ATM appears to be altered in 5.26% of men, and no alterations were depicted in women." (PMID 35330454, 2022).
tumor (17 papers, 2014 to 2023). "In the colony formation assay, both DLD1 and SW480 cells showed adaptive resistance to the MEKi AZD6244, and knockdown of PDE4DIP restored the susceptibility of tumor cells to AZD6244 treatment." (PMID 37355626, 2023). "The GNAS (OMIM-139320, NM_000516.6) (p.R201H, c.602G > A) pathogenic variant in addition to the PDE4DIP p.S977I missense variant was observed in the tumor sample from patient #3." (PMID 32098292, 2020). "Furthermore, we found that knockdown of PDE4DIP restored the susceptibility of tumor cells to MEKi treatment." (PMID 37355626, 2023). "Our findings suggest that NF1 is the downstream transducer of PDE4DIP signaling and that the growth advantage of tumor cells with high PDE4DIP expression is most likely conferred by overactivation of oncogenic RAS signaling due to loss of NF1." (PMID 37355626, 2023). "In 48 of the 60 (80%) primary CRC tumors, the PDE4DIP transcript level was increased in tumor samples compared with the matched adjacent normal mucosa samples." (PMID 37355626, 2023). "In this study, we showed that knockdown of PDE4DIP impaired KRAS-mutant CRC tumor growth through suppression of oncogenic RAS/ERK/AKT signaling." (PMID 37355626, 2023). "Our study shows that PDE4DIP confers adaptive MEKi resistance and affects tumor growth through a similar NF1/RAS/ERK signaling axis." (PMID 37355626, 2023). "In contrast, stable overexpression of full-length PDE4DIP in DLD1 cells significantly increased the colony-forming capacity of tumor cells." (PMID 37355626, 2023). "Another important finding of our study is that PDE4DIP affects KRAS-mutant CRC tumor growth via PKCε-mediated destabilization of NF1." (PMID 37355626, 2023). "Gene set enrichment analysis (GSEA) of the TCGA dataset and two other GEO cohorts also revealed that the gene sets related to MAPK and mTOR/AKT signaling pathways were enriched in tumor samples with high PDE4DIP expression." (PMID 37355626, 2023). "This PDE4DIP function is necessary for cell stability at the leading edge of migrating cells, and its influence on tumor cell motility and proliferation is vital in tumor development." (PMID 35805104, 2022). "In one CCA tumor and two HCC tumors we identified recurrent mutations in PDE4DIP (Phosphodiesterase 4D Interacting Protein), a gene involved in cAMP signaling and a known driver gene in HCC34." (PMID 31796844, 2019). "Two genes, PDE4DIP (mutated in 4 tumours) and MUC16 (mutated in 2 tumours) carried 11 somatic variations each, making them the most mutated genes in the dataset." (PMID 27829003, 2016). "To assess the effect of PDE4DIP on tumor growth in vivo, we subcutaneously injected DLD1 and SW480 cells stably transduced with lentiviral vectors harboring scrambled control shRNA (shNC) or PDE4DIP shRNA into nude mice and then monitored the growth of the resultant tumors." (PMID 37355626, 2023). "Moreover, pretreatment with the RAS inhibitor salirasib (S-farnesylthiosalicylic acid, FTS) not only blocked PDE4DIP-promoted ERK/AKT phosphorylation but also nullified the promoting effect of PDE4DIP on tumor cell growth." (PMID 37355626, 2023). "Moreover, pretreatment with MEK or AKT inhibitors attenuated PDE4DIP-promoted tumor cell proliferation." (PMID 37355626, 2023). "Overall, our data indicate that PDE4DIP may play a role in tumor development by promoting tumor cell proliferation and migration, making it an appealing target for the treatment of a variety of malignant tumors." (PMID 35805104, 2022). "Taken together, these data indicate that PKCε activation plays an essential role in PDE4DIP-promoted NF1 degradation and CRC tumor growth." (PMID 37355626, 2023). "In order to better clarify the role of PDE4DIP in LAML and its relationship with immune response, TME, and tumor purity, we conducted correlation analyses between PDE4DIP expression and estimate score, immune score, normal score, and TumorPurity score." (PMID 37663233, 2023).
tumor (continued). "We compared the correlation of BC patient clinical information (age, menopause status, metastasis, tumor stage, and tumor subclass) to GBP1 and PDE4DIP expression." (PMID 38072995, 2023). "Together, these results suggest that downregulation of NF1 plays an essential role in PDE4DIP-promoted overactivation of RAS/ERK/AKT signaling and CRC tumor growth." (PMID 37355626, 2023). "To explore the dysregulation of PDE4DIP in CRC, we analyzed PDE4DIP mRNA expression in primary human CRC tumor samples." (PMID 37355626, 2023). "Gene Ontology (GO) and Kyoto Encyclopedia of Genes and Genomes (KEGG) enrichment analyses showed that tumor growth- and cell survival-related pathways (MAPK and GTPase activity) were predominant among the downregulated pathways in PDE4DIP-silenced cells." (PMID 37355626, 2023). "Four SNVs of NOTCH2, PDE4DIP, ATP10B and NSD1 and one frameshift INDEL of BAP1 were validated by Sanger sequencing on tumour RNA." (PMID 28484631, 2017). "As we all know, PDE4DIP is a protein that can interact with cAMP-specific PDE4D and is widely expressed in various cell types, including neurons, cardiomyocytes, immune cells, and tumor cells, and participates in cell proliferation, migration, and cell cycle." (PMID 37663233, 2023).
adenocarcinoma (1 paper, 2022). A common cancer characterized by the presence of malignant glandular cells. "The PDE4DIP (Phosphodiesterase 4D Interacting Protein) that anchors phosphodiesterase in centrosomes was shown to co-express with the endogenous tumor suppressor gene THBS1, and high expression levels of PDE4DIP were associated with improved survival rates in adenocarcinoma patients." (PMID 36552904, 2022).
PDE4DIP also shares sentences with these, for which no sentence is quoted: esophageal cancer (2 papers); frontotemporal dementia (2); gastric cancer (2); ischemic stroke (2); non-small cell lung carcinoma (2); ovarian carcinoma (2); pancreatic cancer (2); vascular dementia (2); Alzheimer disease (1); atrial fibrillation (1); autoimmune disease (1); bladder cancer (1); cervical squamous cell carcinoma (1); childhood asthma (1); clear cell renal cell carcinoma (1); colon adenocarcinoma (1); craniofacial microsomia (1); diabetic neuropathy (1); endocervical adenocarcinoma (1); eosinophilia (1); head and neck squamous cell carcinoma (1); heart failure (1); hematological malignancies (1); infection (1); Intellectual disability (1); ischemia (1); laryngeal tumors (1); lymphoma (1); major depressive disorder (1); medullary thyroid cancer (1).
A further 16 diseases each share a sentence with PDE4DIP in 1 paper.